GSTZ1 (glutathione S-transferase zeta 1)
Description:
Bifunctional enzyme showing minimal glutathione-conjugating activity with ethacrynic acid and 7-chloro-4-nitrobenz-2-oxa-1,3-diazole and maleylacetoacetate isomerase activity. Also has low glutathione peroxidase activity with T-butyl and cumene hydroperoxides. Is able to catalyze the glutathione dependent oxygenation of dichloroacetic acid to glyoxylic acid.
Synonyms: MAAI; GSTZ1-1; MAI; MAAID
Tractability: PROTAC: its protein half-life has been measured.
Target class: Enzyme
Gene: Protein-coding gene on chromosome 14 (77,320,996 to 77,331,597, forward strand). Ensembl gene ENSG00000100577.
Subcellular location: Cytoplasm
Subcellular location (Human Protein Atlas): Cytosol; Nucleoplasm
Pathways (Reactome):
Metabolism: Glutathione conjugation; Regulation of pyruvate dehydrogenase (PDH) complex; Tyrosine catabolism
Gene Ontology:
Molecular function: glutathione transferase activity; identical protein binding; maleylacetoacetate isomerase activity; protein binding; protein homodimerization activity; glutathione peroxidase activity; catalytic activity
Biological process: cellular detoxification; glutathione metabolic process; L-phenylalanine catabolic process; aromatic amino acid metabolic process; cellular oxidant detoxification
Cellular component: cytosol; mitochondrion; mitochondrial matrix; cytoplasm
Genetic constraint (gnomAD): Loss-of-function variants: 20 observed, 21.65 expected, observed/expected ratio (o/e) 0.92, 90% interval 0.65 to 1.34. The upper end of that interval is the gene's LOEUF score, 1.34, which puts it in group 5 of 6, group 1 being the genes least tolerant of losing a copy. Missense variants: 201 observed, 210.09 expected, observed/expected ratio (o/e) 0.96, 90% interval 0.85 to 1.08. Synonymous variants: 74 observed, 80.57 expected, observed/expected ratio (o/e) 0.92, 90% interval 0.76 to 1.11.
Gene-disease validity (ClinGen):
ClinGen rates the evidence that GSTZ1 causes each of these diseases.
maleylacetoacetate isomerase deficiency (autosomal recessive): Moderate.
Homologues: Orthologues: chimpanzee GSTZ1 (97% identical), rat Gstz1 (86% identical), mouse Gstz1 (85% identical), dog GSTZ1 (85% identical), rabbit GSTZ1 (85% identical), pig GSTZ1 (79% identical), macaque GSTZ1 (75% identical), tropical clawed frog gstz1 (72% identical), guinea pig GSTZ1 (68% identical), zebrafish gstz1 (65% identical), Drosophila melanogaster GstZ2 (58% identical), Drosophila melanogaster GstZ1 (56% identical), and 1 more. Paralogues in human: GSTO1 (27% identical), GSTO2 (26% identical), CLIC4 (21% identical), CLIC6 (21% identical), GSTT2B (21% identical), GSTT2 (21% identical), CLIC5 (20% identical), CLIC2 (20% identical), CLIC1 (19% identical), GSTT4 (18% identical), GDAP1 (16% identical), CLIC3 (16% identical), and 2 more.
Diseases named in the same sentence as GSTZ1 in open-access papers:
GSTZ1 is named in the same sentence as 43 diseases in open-access papers, as found by Europe PMC text mining. Sharing a sentence is not in itself a finding about the gene and the disease. The quoted sentences say what the papers report.
hepatocellular carcinoma (19 papers, 2018 to 2025). A malignant tumor that arises from hepatocytes. "Here, we aimed to explore the crosstalk between dysregulated glucuronic acid metabolism and crucial metastatic signalling in glutathione S‐transferase zeta 1 (GSTZ1)‐deficient hepatocellular carcinoma (HCC)." (PMID 35979621, 2022). "UDP‐glucose 6‐dehydrogenase (UGDH)‐mediated UDP‐glucuronic acid (UDP‐GlcUA) accumulation promoted hepatoma cell migration upon GSTZ1 loss." (PMID 35979621, 2022). "Our in vitro and in vivo gain- and loss-of-function studies revealed that GSTZ1 suppressed the Warburg effect and proliferation in hepatoma cells, indicating that GSTZ1 plays a tumor suppressor role in HCC." (PMID 31666108, 2019). "Given that the metabolite SA is structurally similar to α-KG, an important regulator of the PHD2/HIF-1α axis, we assumed that accumulated SA may be responsible for activating the HIF-1α signaling pathway in GSTZ1-deficient hepatoma cells." (PMID 37906252, 2023). "Collectively, these findings indicated that the inhibition of NRF2 could markedly sensitize GSTZ1-deficient hepatoma cells to sorafenib treatment." (PMID 33931597, 2021). "Thus, we detected the expression of IGF1R, and its downstream genes and apoptosis‐associated proteins, in gain and loss of GSTZ1‐1 hepatoma cells." (PMID 31267557, 2019). "Therefore, we investigated whether the antioxidant agent N-acetylcysteine (NAC) or the NRF2 inhibitor brusatol (Bru) could suppress proliferation in GSTZ1-deficient hepatoma cells." (PMID 31666108, 2019). "In contrast to the AdGFP control, GSTZ1 overexpression significantly suppressed the metastatic potential of HCC cells, while GSTZ1 loss endowed hepatoma cells with the ability to colonize the lungs and form metastatic lesions." (PMID 35979621, 2022). "Non‐targeted and targeted metabolomics and global transcriptomic analyses were performed to screen significantly altered metabolic and signalling pathways in GSTZ1 overexpressing hepatoma cells." (PMID 35979621, 2022). "Meanwhile, the expression of Nrf2 is suppressed by Glutathione S-transferase zeta 1 (GSTZ1), which ia an enzyme in the catabolism of phenylalanine significantly downregulated in sorafenib-resistant hepatoma cells." (PMID 36105219, 2022). "Together, these results suggested that GSTZ1 increased the sensitivity of hepatoma cells to sorafenib by inducing ferroptosis." (PMID 33931597, 2021). "Glutathione S‐transferase Zeta 1‐1 (GSTZ1‐1), an enzyme involved in the catabolism of phenylalanine and the detoxification of xenobiotics, plays a tumour suppressor role in hepatocellular carcinoma." (PMID 31782257, 2020). "In summary, our transcriptomic results indicate, for the first time, that GSTZ1‐1 can downregulate Wnt/β‐catenin signalling in hepatoma cells." (PMID 31782257, 2020). "In the present work, we aimed to comprehensively identify differentially expressed gene (DEG) profiles related to GSTZ1‐1 overexpression in hepatoma cells." (PMID 31782257, 2020). "High levels of GSTZ1 expression conferred resistance to the effect of anti-cancer therapy of dichloroacetate in hepatocellular carcinoma cell lines by an independent mechanism to tyrosine metabolism." (PMID 32542016, 2020). "This study shows that oxidative stress was significantly reduced in GSTZ1-overexpressing hepatoma cells but elevated in GSTZ1-KO hepatoma cells." (PMID 31666108, 2019). "Herein, GSH depletion was demonstrated in the GSTZ1-KO hepatoma cells and the liver of Gstz1−/− mice, concurrent with our previous study on Gstz1−/− mice." (PMID 31666108, 2019). "The effect of GSTZ1 on the expression of ARE-dependent genes was analyzed using an ARE-regulated luciferase reporter plasmid (pGL3-ARE) in hepatoma cells." (PMID 31666108, 2019). "Our results suggest that GSTZ1 deficiency results in GSH depletion, followed by elevation of oxidative stress and sustained NRF2 activation, thus promoting proliferation in hepatoma cells." (PMID 31666108, 2019).
hepatocellular carcinoma (continued). "To evaluate the role of GSTZ1‐1 in HCC, we first checked endogenous GSTZ1‐1 levels in a collection of hepatoma cell lines and MIHA cells (an immortalized human hepatocyte cell line)." (PMID 31267557, 2019). "To investigate the role of GSTZ1 in HCC, we first determined endogenous GSTZ1 protein levels in some hepatoma cell lines." (PMID 31666108, 2019). "Western blotting revealed that GSTZ1 was substantially downregulated in most hepatoma cells, consistent with our previous study." (PMID 31666108, 2019). "Mechanistic investigation suggested high levels of GSTZ1 expression conferred resistance to the effect of anti-cancer therapy of dichloroacetate in hepatocellular carcinoma cell lines." (PMID 29910195, 2018). "GSTZ1 is downregulated in hepatocellular carcinoma, while it is upregulated in breast cancer." (PMID 38931411, 2024). "GSTZ1 expression is negatively correlated with VEGFA in hepatoma cell lines and human HCC tissues." (PMID 37906252, 2023). "To determine whether GSTZ1‐KO cells would also show increased metastatic potential in vivo, we injected hepatoma cells into the tail veins of BALB/c nude mice." (PMID 35979621, 2022). "On the other hand, GSTZ1 is considered to be a tumor suppressor in hepatocellular carcinoma cells." (PMID 35562974, 2022). "Given the contribution of the enhanced glucuronate pathway and TGFβ signalling to hepatoma cell migration upon GSTZ1 knockout, we determined whether blockage of the glucuronate pathway or TGFβ signalling dampens Gstz1‐deletion dependent tumour promotion." (PMID 35979621, 2022). "In hepatocellular carcinoma cells, GSTZ1 also serves as a tumor suppressor." (PMID 33802702, 2021). "GSTZ1 was significantly downregulated in sorafenib-resistant hepatoma cells." (PMID 33931597, 2021). "Glutathione S‐transferase Zeta 1‐1 (GSTZ1‐1), an enzyme involved in the catabolism of phenylalanine and the detoxification of xenobiotics, plays a tumour suppressor role in hepatocellular carcinoma (HCC), but the underlying mechanism remains largely unknown." (PMID 31782257, 2020). "We examined ROS production in hepatoma cells with different GSTZ1 expression levels." (PMID 31666108, 2019). "GSTZ1‐1 protein expression was substantially lower in most hepatoma cells than in MIHA cells." (PMID 31267557, 2019). "Since GSTZ1 is a metabolic enzyme and most cancer cells perform aerobic glycolysis, we investigated whether GSTZ1 affects the metabolic state of hepatoma cells, using a Seahorse Bioscience XFe24 analyzer." (PMID 31666108, 2019). "Moreover, overexpression of GSTZ1 (p < 0.01) significantly decreased the glycolytic rate of hepatoma cells, whereas Gstz1-KO (p < 0.05) had the opposite effect." (PMID 31666108, 2019). "Here, we found that GSTZ1‐1 could downregulate Wnt/β‐catenin signalling in hepatoma cells." (PMID 31782257, 2020). "We suggest that loss of GSTZ1‐1 results in the accumulation of the oncometabolite SA, alkylation of KEAP1, and NRF2 activation, promoting IGF1R transcription by recruiting SP1 to its promoter, which promotes the antiapoptotic pathway of hepatoma cells in vitro and in vivo." (PMID 31267557, 2019). "Downregulation of GSTZ1 expression has been found in human hepatocellular carcinoma (HCC) tissues." (PMID 41009955, 2025). "Our previous work found that decreased tyrosine metabolism promotes cell cycle in hepatocellular carcinoma, and we found that down-regulation of HGD and GSTZ1 also promotes cell cycle in KIRC." (PMID 35562974, 2022). "The downregulation of tyrosine metabolism pathway-related genes (HPD, HGD, GSTZ1, and FAH) was observed in hepatocellular carcinoma and indicated poor prognosis; however, investigation of dysregulation of tyrosine metabolism pathways in OSCC is lacking." (PMID 34422810, 2021). "To further assess the function of GSTZ1‐1 in HCC, we performed RNA‐Seq to identify the DEGs between GSTZ1‐1‐overexpressing hepatoma cells and control cells." (PMID 31782257, 2020).
hepatocellular carcinoma (continued). "GSTZ1 is dysregulated in cancers; however, its role in tumorigenesis and progression of hepatocellular carcinoma (HCC) is largely unknown." (PMID 31666108, 2019). "In hepatocellular carcinoma, GSTZ1 exerts tumor-suppressive effects: its downregulation leads to succinylacetone accumulation, activating the NRF2 signaling pathway and thereby promoting hepatocellular carcinoma progression." (PMID 41474538, 2025). "GSTZ1 could decrease the protein but not mRNA level of HIF-1α under hypoxia in hepatoma cells, indicating that GSTZ1 may negatively modulate HIF-1α expression at the protein level." (PMID 37906252, 2023). "This suggests that GSTZ1 S14A failed to sensitize hepatoma cells to sorafenib-induced ferroptosis." (PMID 33931597, 2021). "Moreover, a correlation analysis of 363 patients with HCC included in the TCGA Liver Hepatocellular Carcinoma (LIHC) dataset showed a negative correlation between mRNA expression of GSTZ1‐1 and IGF1R (r = −0.31, P < 0.0001, n = 363)." (PMID 31267557, 2019).
liver cancer (7 papers, 2019 to 2023). An epithelial or non-epithelial malignant neoplasm that arises from the liver. "Glutathione transferase zeta 1 (GSTZ1), the enzyme responsible for conversion of dichloroacetate to its inactive metabolite, is observed to decline in liver cancer but increase in BC, the underlying mechanism of which associated with FA metabolism in BC demands further investigations." (PMID 35432381, 2022). "GSTZ1 decreases levels of reduced GSH in liver cancer tissues and thereby inhibits tumor progression." (PMID 36291099, 2022). "The level of GSTZ1 protein was also found to be decreased in BRCA, colon cancer, KIRC, pancreatic cancer, head and neck cancer, and liver cancer." (PMID 36291099, 2022). "To further identify how GSTZ1‐1 mediates IGF1R in hepatocarcinogenesis in vivo, we used the DEN/CCl4‐induced mouse model of liver cancer." (PMID 31267557, 2019). "In addition, LINC00907 (logFC = −2.6057), CCN1 (logFC = −2.05925), GSTZ1 (logFC = −2.34197), and GSTM5 (logFC = −2.8954) were lowly expressed in liver cancer tissues." (PMID 36685007, 2023). "Previous studies also showed that genes from tyrosine metabolism reprogramming (TAT, HPD, HGD, GSTZ1, and FAH) may be used as prognostic biomarkers in liver cancer." (PMID 35847355, 2022).
bladder cancer (6 papers, 2010 to 2025). "GSTZ1 belongs to the zeta class of GSTs, and patients carrying GSTZ1 variants had an increased risk of bladder cancer when exposed to trihalomethanes, a potential human carcinogen." (PMID 29910195, 2018). "Glutathione S-transferase zeta 1 (GSTZ1) enhances ferroptosis through the HMGB1/GPX4 pathway in bladder cancer cells, indicating that HMGB1 promotes ferroptosis via inhibiting the pathways related to antioxidant defenses." (PMID 39994144, 2025). "Polymorphisms: GSTO2*N142D (A424G; rs156697) and other GSTs (GSTP1, GSTM1, GSTT1, GSTZ1)Main findings:- positive association between GSTO2*N142D variant and bladder cancer risk independently of arsenic exposure." (PMID 40724836, 2025). "Associations between THMs and bladder cancer were stronger among subjects who were GSTT1 +/+ or +/− versus GSTT1 null (pinteraction = 0.021), GSTZ1 rs1046428 CT/TT versus CC (pinteraction = 0.018), or CYP2E1 rs2031920 CC versus CT/TT (pinteraction = 0.035)." (PMID 20675267, 2010). "In this study we investigated the combined influence of DBP exposure and polymorphisms in glutathione S-transferase (GSTT1, GSTZ1) and cytochrome P450 (CYP2E1) genes in the metabolic pathways of selected by-products on bladder cancer in a hospital-based case–control study in Spain." (PMID 20675267, 2010). "The consistency of these findings with experimental observations of GSTT1, GSTZ1, and CYP2E1 activity strengthens the hypothesis that DBPs cause bladder cancer and suggests possible mechanisms as well as the classes of compounds likely to be implicated." (PMID 20675267, 2010). "Haplotype analysis for GSTZ1 did not reveal notable elevated or lowered risk of bladder cancer." (PMID 20675267, 2010). "Another GST family member, glutathione S-Transferase zeta 1 (GSTZ1), inhibits ferroptosis in bladder cancer cells." (PMID 38844964, 2024). "We calculated the main effects for the respective SNPs within increasing quartile strata of long-term average THMs where we found increasing relative risks for bladder cancer for GSTT1 present, GSTZ1 rs1046428 CT/TT, and CYP2E1 rs2031920 CC." (PMID 20675267, 2010). "We estimated effects of THMs and GSTT1, GSTZ1, and CYP2E1 polymorphisms on bladder cancer using adjusted logistic regression models with and without interaction terms." (PMID 20675267, 2010).
breast carcinoma (5 papers, 2007 to 2024). "Recently, GSTZ1‐1 was reported to be downregulated in HCC and upregulated in breast cancer, indicating that dysregulation of GSTZ1‐1 may be involved in the tumorigenesis in humans." (PMID 31267557, 2019). "In contrast, GSTZ1 is reportedly upregulated in breast cancer." (PMID 31666108, 2019). "Furthermore, GSTZ1 may play different roles in different tumor cell types, although limited information is available regarding its exact role in breast cancer." (PMID 31666108, 2019). "GSTZ1 was recently reported to be downregulated in HCC and upregulated in breast cancer, indicating that GSTZ1 dysregulation may be involved in tumorigenesis in humans." (PMID 31666108, 2019).
lung carcinoma (4 papers, 2022 to 2026). "We were not able to find any published data referring to the association of GSTZ1 and OS in lung cancer patients of any subtype." (PMID 38398111, 2024). "In this study, we continue to focus on the germline mutation of genes in lung adenocarcinoma and we have identified seven different variants (SMG5, RAB3GAF2, EI24, XDH, PTPRA, ATR, GSTZ1) in three sibling patients suffering from lung cancer." (PMID 35712480, 2022). "Glutathione S-transferase zeta 1 (GSTZ1) is a metabolic enzyme that regulates cell metabolism; however, its role in KRAS-driven lung cancer remains underexplored." (PMID 42240478, 2026). "Analysis of 15 GST isoforms of human lung cancer using the TCGA dataset showed GSTP1, GSTA2, GSTA5, GSTO2, and GSTZ1 were significantly upregulated in LUAD compared to corresponding normal tissues, suggesting their potential oncogenic effects on LUAD." (PMID 36709476, 2023).
ovarian carcinoma (3 papers, 2014 to 2019). A malignant neoplasm originating from the surface ovarian epithelium. "We constructed a three-gene prognostic signature consisting of TXNRD1, GLA and GSTZ1 which was associated with overall survival for ovarian cancer patients received platinum-based chemotherapy, especially in those with elder age, high pathological grade and advanced tumor stage." (PMID 29910195, 2018). "In the present study, we, for the first time, identified a panel of three oxidative stress-related genes, including TXNRD1, GLA and GSTZ1, to predict overall survival for ovarian cancer patients." (PMID 29910195, 2018). "In this study, we found GSTZ1 might act as a protective factor in ovarian cancer, suggesting that altered GSTZ1 expression level might have impact on survival by affecting the toxic of chemotherapy." (PMID 29910195, 2018). "Notably, the MetaGx signature included 3 genes (DDB2, GSTZ1, and FAM1892A) that had been previously identified from the set of 12 genes sharing same-direction hazard ratios in the meta-analysis of breast and ovarian cancers." (PMID 31217513, 2019).
tyrosinemia type I (3 papers, 2024 to 2025). "For further diagnostic work-up, a virtual panel from exome sequencing focusing on the genes FAH (Tyrosinemia type I, MIM #276700) and GSTZ1 (Maleylaceoacetate Isomerase Deficiency, MIM #617596) was performed in leucocyte-derived DNA of the index." (PMID 38535121, 2024). "Screening for tyrosinemia type I (FAH, MIM *613871, #276700) using DBS succinylacetone as a biomarker had a PPV of 9% from 2018 to 2022, this biomarker often reveals variants in GSTZ1 (MIM *603758, #617596), which causes the non-clinical entity maleylacetoacetate isomerase deficiency." (PMID 39846587, 2024).
(MAAI) deficiency (2 papers, 2024 to 2025). "Recently, biallelic pathogenic variants in GSTZ1 underlying maleylacetoacetate isomerase (MAAI) deficiency have been described as a differential diagnosis in individuals with slightly elevated succinylacetone detected by NBS." (PMID 38535121, 2024).
Anxiety (2 papers, 2016 to 2020). Intense feelings of nervousness, tension, or panic often arise in response to interpersonal stresses. "It is worth knowing, however, that biological pathways associated with SLC1A1 and GSTZ1 seem to be related to anxiety symptoms in general, rather than to social anxiety specifically." (PMID 32507125, 2020).